SPARC (secreted protein acidic and cysteine rich)
Diseases named in the same sentence as SPARC in open-access papers (continued):
Sharing a sentence is not in itself a finding about the gene and the disease.
gastric cancer (continued). "In vitro western blotting and immunofluorescence staining further demonstrated that human gastric cancer cells (MKN-45 and AGS) did not produce SPARC." (PMID 29156791, 2017). "We performed Quantitative Real-time PCR (qPCR) on 6 up-regulated genes (COL1A, BGN, SPP1, MELK, IGFBP4, SPARC) and 4 down-regulated genes (PGC, SST, MT1X, S100P) to verify our data in gastric cancer tissues (Tumor) and noncancerous tissues (Normal)." (PMID 25928635, 2015). "In gastric cancer tissue, most of TAM did not express SPARC." (PMID 29156791, 2017). "Our study showed that TLN2, SRPX2 and SPARC expression were detected in gastric cancer, but expression of TLN2, SRPX2 and SPARC could not differentiate preoperative gastric cancer patients from healthy volunteers." (PMID 23548070, 2013). "SPARC was not expressed by CD31-positive cells in normal gastric tissue but was detected in the neovascular endothelial cells of gastric cancer tissue, suggesting that neovascular endothelial cells would be an additional source of SPARC in gastric cancer tissue." (PMID 29156791, 2017).
ovarian carcinoma (56 papers, 2006 to 2025). A malignant neoplasm originating from the surface ovarian epithelium. "The expression of SPARC in ovarian cancer cells was negatively associated with the level of malignancy." (PMID 37577749, 2023). "Malignant ascites is the most common cause of death from ovarian cancer, and SPARC normalizes malignant ascites in the ovarian cancer microenvironment and improves inflammation through downregulating the VEGF–integrin–MMP axis." (PMID 37577749, 2023). "Second, signatures increased in collagen expression together with LOX, THBS2, TIMP3 and SPARC have also been associated with decreased survival in ovarian cancer." (PMID 33379263, 2020). "High SPARC expression was associated with high stage, low differentiation, lymph node metastasis and poor prognosis of ovarian cancer." (PMID 22879971, 2012). "In conclusion, overexpression of SPARC is associated with tumor progression of human ovarian cancer." (PMID 22879971, 2012). "Further analysis of SPARC expression in 140 human ovarian tissues revealed that SPARC was overexpressed in malignant ovarian tumors and associated with poor clinicopathologic features." (PMID 22879971, 2012). "SPARC expression could inhibit the production of interleukin-6 in ovarian cancer tissues and decrease levels of peritoneal metastasis caused by ovarian cancer." (PMID 35211625, 2022). "Interestingly, it was suggested that while loss of endogenous SPARC in a mouse model of ovarian cancer increased tumor growth, it also increased the response to cisplatin chemotherapy." (PMID 27622658, 2016). "Moreover, high SPARC expression was associated with low differentiation, high stage and positive lymph node status of ovarian carcinomas." (PMID 22879971, 2012). "Differential expression of SPARC, a tumor suppressor gene implicated in ovarian cancer, has been shown to give consistent expression profiles in EOC cell lines and samples across a number of Affymetrix GeneChip® platforms and by RT-PCR from our group and others." (PMID 19580657, 2009). "SPARC, a putative tumour suppressor whose high expression levels were found associated with advanced stage, low differentiation, lymph node metastasis and poor prognosis of ovarian cancer, was also significantly overexpressed in the CAFs‐immune subtype (P < 0.001)." (PMID 33522069, 2021). "In bone, NF-kB activation was shown to stimulate SPARC, and SPARC inhibited the metabolic programming of ovarian cancer cells and adipocytes by an NF-kB-mediated mechanism." (PMID 38994944, 2024). "In humans, previous studies demonstrate several tumor-suppressive roles of SPARC in ovarian cancer cells." (PMID 37158892, 2023). "SPARC promoter methylation is an essential element in the occurrence and survival of ovarian cancer, and SPARC can be used as a therapeutic target and predictive marker for ovarian cancer." (PMID 37577749, 2023). "Knocking down SPARC production clearly reduced ovarian cancer cell proliferation, induced the apoptosis, and prevented the cells from invading and metastasizing." (PMID 37577749, 2023). "SPARC becomes a key factor in ovarian cancer development as it is overexpressed in aggressive subclones and ovarian cancer samples." (PMID 37577749, 2023). "SPARC helps normalize the ovarian cancer malignant ascites microenvironment by downregulating the VEGF–integrin–MMP axis, reducing the levels and activation of bioactive lipids, and ameliorating downstream inflammatory." (PMID 37577749, 2023). "SPARC suppresses the differentiation of ovarian cancer cells and transition of adipocytes to cancer." (PMID 37577749, 2023). "It has been suggested that SPARC exerts the tumor suppressor effects in ovarian cancer through inhibition of cEBPβ, NFkB, AP-1, and their downstream inflammatory effects." (PMID 34751020, 2022). "SPARC expression was significantly lower in ovarian cancer tissues than in normal tissues and in patients with a poorly differentiated and larger omentum." (PMID 35211625, 2022).
ovarian carcinoma (continued). "SPARC, which has anti-inflammatory and inhibitory effects in ovarian cancer cells, is also related to obesity-induced insulin resistance." (PMID 34751020, 2022). "Among the inhibitory mechanisms, the effect of SPARC on metabolism is mainly to inhibit the metabolic reprogramming of adipocytes and ovarian cancer cells, inhibit adipocyte differentiation, and inhibit adipocytes from acquiring cancer-related phenotypes." (PMID 33926551, 2021). "Depletion of SPARC strongly suppressed migration activity and admixture of rSPARC partially rescued the effect, which has also been described for ovarian cancer." (PMID 31554208, 2019). "Other genes such as FAP, CTSK, FBN1, THBS2, SPARC, and COL1A1 are also known to be ovarian cancer associated." (PMID 27843486, 2016). "Recent data, utilizing an ovarian cancer syngeneic mouse model, suggests that the presence of host secreted SPARC limits peritoneal dissemination and ascites formation." (PMID 27622658, 2016). "In this module, 5 genes (FN1, MMP2, MMP1, PLAU, and SPARC), colored in green, were identified as ovarian cancer-related genes in the DDOC database." (PMID 25611546, 2015). "Recently, Socha and colleagues reported that secreted protein acidic and rich in cysteine (SPARC) is down-regulated in ovarian cancer through aberrant promoter hypermethylation." (PMID 23613894, 2013). "Knockdown of SPARC suppressed ovarian cancer cell proliferation, induced cell apoptosis and inhibited cell invasion and metastasis." (PMID 22879971, 2012). "But in our study, by lentivirus-mediated RNA interference, we found that knockdown of SPARC expression suppressed cell proliferation, induced cell apoptosis, and inhibited cell invasion and metastasis in ovarian cancer cells." (PMID 22879971, 2012). "To understand the mechanism by which the proliferation of ovarian cancer cells was inhibited by knockdown of SPARC expression, we used flow cytometry to identify the specific phases of cell cycle." (PMID 22879971, 2012). "SPARC is overexpressed in highly invasive subclone and ovarian cancer tissues and plays an important role in ovarian cancer growth, apoptosis and metastasis." (PMID 22879971, 2012). "All of these informations contribute to a better understanding that intracellular SPARC, as a promoter, improves ovarian cancer cell proliferation, invasion and metastasis." (PMID 22879971, 2012). "In contrast, with the antibody LF-54, another study indicated that SPARC expression is down-regulated in ovarian cancer; exogenous SPARC inhibited the proliferation and induces apoptosis in ovarian cancer cells." (PMID 22879971, 2012). "Another research revealed that exogenous SPARC inhibited αv- and β1- mediated adhesion of ovarian cancer cells to ECM." (PMID 22879971, 2012). "In our study, with the antibody AF941 and bs-1133R, we found that the immunoreactivity of SPARC was heightened not only in stroma but also in the cytoplasm of ovarian cancer cells." (PMID 22879971, 2012). "In functional assays, effects of SPARC knockdown on the biological behavior of ovarian cancer cells were investigated." (PMID 22879971, 2012). "To evaluate the prognostic value of SPARC in ovarian cancer, we performed survival analysis using Kaplan-Meier analysis." (PMID 22879971, 2012). "The mechanisms of SPARC in ovarian cancer proliferation, apoptosis and invasion were also researched." (PMID 22879971, 2012). "Knockdown of SPARC expression significantly suppressed ovarian cancer cell proliferation, induced cell apoptosis and inhibited cell invasion and metastasis." (PMID 22879971, 2012). "In this study, using MTT assay and soft agar colony formation assay, we concluded that knockdown of SPARC suppressed ovarian cancer cell proliferation." (PMID 22879971, 2012). "Overexpression of SPARC by ovarian carcinoma cells led to increased tumour cell apoptosis, and the levels of SPARC were inversely correlated with tumour progression in vivo." (PMID 20087345, 2010).
ovarian carcinoma (continued). "The SPARC exerts growth inhibitory activity on immortalised ovarian cancer cells in vitro and in mouse xenograft explants." (PMID 20087345, 2010). "An inhibitory effect of SPARC on proliferation and migration has been found in breast and ovarian carcinoma cells." (PMID 20087345, 2010). "In contrast, in ovarian cancer, elevated SPARC expression inhibited the invasion and metastasis of tumor cells." (PMID 20565704, 2010). "For example, in ovarian cancer cells, exogenous exposure to SPARC resulted in the enhanced apoptosis, whereas endogenous absence of it diminished apoptosis." (PMID 20565704, 2010). "Said and Motamed found SPARC exposure increased cleaved caspase 3 in human ovarian carcinoma cells which supported the former observation." (PMID 20525171, 2010). "Yiu and colleagues showed that exogenous treatment of various ovarian cancer cell lines with SPARC induced apoptosis." (PMID 20525171, 2010). "Pancreatic and ovarian cancers exhibited greater growth and reduced apoptosis when implanted in SPARC-/-." (PMID 20525171, 2010). "The SPARC functions as a tumour suppressor in neuroblastoma, breast, pancreatic, lung and ovarian cancers." (PMID 20087345, 2010). "SPARC may work as a tumor suppressor to reduce angiogenesis and lymphangiogenesis in ovarian cancer by decreasing the amount of VEGF-C and VEGF-D expression." (PMID 37577749, 2023). "SPARC inhibits the NF-κB pathway mediating macrophage-induced ovarian cancer cell invasion." (PMID 37577749, 2023). "SPARC inhibits the αv- and β1-integrin-mediated attachment of ovarian cancer cells to the ECM." (PMID 37577749, 2023). "Additionally, secreted protein acidic and rich in cysteine (SPARC) is known as a key regulator of apoptosis and invasion in ovarian cancer." (PMID 36765641, 2023). "SPARC curbs apoptosis and inhibits the aggression and diversion of ovarian cancer cells." (PMID 37577749, 2023). "Moreover, SPARC seemed to inhibit lymphangiogenesis in ovarian cancer through reduced VEGF-C and -D expression." (PMID 35740945, 2022). "This protein has anti-inflammatory properties and tumor suppressor effects in ovarian cancer through inhibition of the metabolic plasticity and mitochondrial bioenergetics; thereby, SPARC inhibits the cancer cell interactions, proliferation, and invasion of ovarian cancer." (PMID 34751020, 2022). "Secreted protein acidic and rich in cysteine (SPARC) can inhibit omental metastasis of ovarian cancer by inhibiting the interaction between ovarian cancer cells and adipocytes, thereby inhibiting the phenotypic plasticity of omental adipocytes and metabolic reprogramming." (PMID 33926551, 2021). "Two identified biomarkers among differentially expressed proteins, SPARC and THBS1, had lower plasma concentrations in healthy BRCA1/2 variant carriers than in ovarian cancer patients with the BRCA1/2 variant; concentration of two proteins increased at the onset of ovarian cancer." (PMID 34064977, 2021). "This may be of relevance, because SPARC has been shown to modulate treatment response in ovarian cancer and interference with sensitivity to radiation and drug exposure in CRC cell lines." (PMID 31554208, 2019). "Even though SPARC is highly expressed in several tumors, it may be able to inhibit tumorigenesis or tumor progression in human ovarian cancer and its expression is reduced in ovarian cancer cell lines." (PMID 30424792, 2018). "However, in ovarian cancer cell, knockdown SPARC expression with shRNA inhibits lung metastasis via tail vein injection of cancer cells." (PMID 28969021, 2017). "SPARC shows an anti-tumor role in anti-angiogenesis, anti-adipogenesis, pro-apoptosis, and inhibition of cell proliferation in several types of cancer, including ovarian cancer, colorectal, neuroblastoma." (PMID 28718842, 2017). "A decrease in SPARC expression has been observed in numerous cancers including acute myeloid leukemia, multiple forms of lung cancer, pancreatic ductal adenocarcinoma, and ovarian carcinoma." (PMID 26926673, 2016).
ovarian carcinoma (continued). "Furthermore, our data suggests that the ability of SPARC to regulate extracellular TGFBI influences both ovarian cancer motility and response to the chemotherapeutic agent, paclitaxel." (PMID 27622658, 2016). "In addition, elevated SPARC levels correlate with increased invasiveness of ovarian cancers and poor prognosis." (PMID 27622658, 2016). "Our data suggested that SPARC, as an antistress factor, could promote ovarian cancer cell survival through suppression of apoptotic pathways." (PMID 22879971, 2012). "In our research, we found that SPARC was not only secreted by the stroma but also secreted by ovarian cancer cells and may exert important intracellular effects upon these cells." (PMID 22879971, 2012). "In this study, we investigated the expression and function of SPARC in ovarian cancer." (PMID 22879971, 2012). "Knockdown of SPARC inhibited ovarian cancer cells invasion and migration." (PMID 22879971, 2012). "Knockdown of SPARC can inhibit ovarian cancer cell growth and invasion." (PMID 22879971, 2012). "Further research showed that knockdown of SPARC induced ovarian cancer cell apoptosis." (PMID 22879971, 2012). "In conclusion, the functions of SPARC in ovarian cancer need further studies." (PMID 22879971, 2012). "Some evidence shows that the overexpression of αvβ3 integrin increases the number and size of bone metastases from ovarian cancer, in addition to increasing the migration of cancer cells towards the bone sialoprotein, which is highly expressed in the bone stroma, similar to SPARC." (PMID 35682554, 2022). "In addition, our findings showed that the methylation levels of candidate genes (HIC1, HOXA9, SOX1, DAPK1, RASSF1A, SFRP1, and SPARC) were significantly elevated in patients with ovarian cancer and was highly cancer-specific, which is in concord with the previously published reports." (PMID 34778370, 2021). "In addition, it has been shown that exogenous SPARC can promote apoptosis in ovarian cancer cells." (PMID 27622658, 2016). "In this process, SPARC may play a role in promoting the invasion and metastasis of ovarian cancer." (PMID 22879971, 2012). "Our data suggested that depletion of SPARC could promote the homophilic cell-cell adhesion by up-regulating E-cadherin and restrained extracellular matrix degradation by down-regulating MMPs activities to inhibit ovarian cancer cell invasion and metastasis." (PMID 22879971, 2012). "SPARC regulates the expression of VEGF-C and VEGF-D in ovarian cancer, thereby affecting angiogenesis and lymphangiogenesis." (PMID 41262238, 2025). "SPARC markedly reduced the proliferative, chemotactic, and invasive effects of LPA on ovarian cancer cell lines." (PMID 37577749, 2023). "Herein, the promoter methylation of seven ovarian cancer-specific genes (RASSF1A, DAPK1, SOX1, HOXA9, HIC1, SPARC, and SFRP1) was analyzed quantitatively in 120 tissue samples by MethyLight assay." (PMID 34778370, 2021). "Although ovarian cancer cells such as PEO1 express and secrete both TGFBI and SPARC, while SKOV3 primarily only express TGFBI, their extracellular matrix is not well organized and the TGFBI fibrillar deposition is almost non-existent." (PMID 27622658, 2016). "In function assay, by lentivirus-mediated RNA interference, we decreased the expression of SPARC in highly invasive subclone S1 and HO8910PM to determine the effect of SPARC on ovarian cancer cell proliferation, apoptosis, invasion and metastasis." (PMID 22879971, 2012).
ovarian carcinoma (continued). "In addition, SPARC shows dose-dependent inhibition of HK2 activity and decreased mitochondrial activity on human and mouse ovarian cancer cell lines, which is related to the energy metabolism of tumor metastasis." (PMID 38076208, 2023). "By intraperitoneal injection of syngeneic ID8 ovarian cancer cells into SPARC-null and wild-type mice, they found that absence of host-derived SPARC dramatically accelerates ascites formation and peritoneal metastasis in vivo." (PMID 22879971, 2012). "Due to the negative correlation among SPARC and ovarian cancer and the regulation of the microenvironment, SPARC could be a possible drug target for curing ovarian cancer." (PMID 37577749, 2023). "Thus, SPARC may modulate the organization of multiple ECM components, subsequently influencing desmoplasia and drug efficacy in ovarian cancer." (PMID 27622658, 2016). "In animal models of ovarian cancer, the absence of SPARC could de-repress the expressions of VEGF, by which to promote the angiogenic and metastatic potential of tumors." (PMID 20565704, 2010). "In addition, the absence of SPARC may promote tumor dissemination, as was illustrated in a mouse ovarian cancer model, although our results would suggest this may not be due to an effect on cell migration." (PMID 27622658, 2016). "Furthermore, ovarian cancer cells have a reduced motility and decreased response to the chemotherapeutic agent paclitaxel when plated on ECM derived from mesothelial cells lacking SPARC compared to control mesothelial-derived ECM." (PMID 27622658, 2016).